SEMA3B (semaphorin 3B)
Diseases named in the same sentence as SEMA3B in open-access papers (continued):
Sharing a sentence is not in itself a finding about the gene and the disease.
tumor (continued). "Class-3 semaphorins, such as sema3A, sema3B, sema3F have been previously characterized as natural tumor suppressors and there are indications that sema3E also may function as a natural tumor suppressor." (PMID 22936999, 2012). "The subgroup discrimination properties of SEMA3B found in the present study, as well as the significantly lower expression observed in tumour groups p2/h2 and p3/h3, could support its tumour suppressor function." (PMID 21492432, 2011). "Indeed, sema3F and sema3B have been found to inhibit the adhesion, migration and proliferation of several types of lung cancer derived tumor cells." (PMID 18818766, 2008). "In these tumours, SEMA3B, SEMA3G and NRP2 expressions were related to prolonged survival." (PMID 18781179, 2008). "Indeed, sema3s such as sema3F and sema3B were reported to inhibit the adhesion, spreading and proliferation of various types of tumor cells." (PMID 18818766, 2008). "Our observation is in accordance with the tumour suppressor activity of SEMA3B." (PMID 18781179, 2008). "The identification of sema3B and sema3F as tumor suppressors, and the identification of sema3F and sema3A as inhibitors of angiogenesis, suggested that additional sema3s may also possess anti-tumorigenic and anti-angiogenic properties." (PMID 18818766, 2008). "Lower mRNA expression of SEMA3B, SEMA3D, SEMA3G, and PLXNA2 or higher mRNA expression of SEMA3F, NRP1, ITGB3, ITGA5, and VEGFA genes were detected in the older patient group and associated with the higher tumor grade, wild-type status of IDH, and lower rate of survival time (p < 0.05)." (PMID 33036421, 2020). "Therefore, it was important to further elucidate particular aspects of SEMA3B tumor suppression." (PMID 25961819, 2015). "This signalling pathway consisted of three secreted proteins (SEMA3A, SEMA3B and SEMA3C), which were correlated with tumour metastasis and unfavourable therapy response." (PMID 39187937, 2024). "In summary, SEMA3B, SEMA3B-AS1, and miR-6872-5p seem to play a suppressor role in GCA tumor development, and their expression levels are coregulated by aberrant promoter hypermethylation and histone modification." (PMID 33537086, 2021). "Sema3B can downregulate phosphatidylinositol 3-kinase (PI3K)/Akt activity in cancer cells, inhibit cellular proliferation and tumor growth 8, as well as metastasis." (PMID 33537086, 2021). "In relation to the malignancy grade of the tumor, mRNA levels of SEMA3B, SEMA3C, SEMA3D, SEMA3G, PLXNA2, and CDH1 decreased while mRNA levels of SEMA3F, NRP1, ITGB3, ITGA5, and VEGFA increased with the increase of the tumor malignancy (p < 0.05)." (PMID 33036421, 2020). "In this study, we confirmed the tumor-suppressive activity of SEMA3B both in vitro (U2020 SCLC cells) and in vivo (SCID mice models, by both tumor growth assay and multi-gene inactivation tests)." (PMID 25961819, 2015). "However, SEMA3B may have both tumor-suppressive and pro-invasive properties." (PMID 25961819, 2015). "The region located between 3p21.3 and 3p14.3, deleted in both cell sub-lines, contains several established tumor suppressor genes including LTF, TDGF1, WNT5a, and RASSF, as well as candidate tumor suppressors such as CACNA2D3, GNAI2, and SEMA3B." (PMID 23951555, 2013). "With the exception of sema3G and sema3B, expression of these semaphorins in U87MG cells inhibited significantly tumor development from subcutaneously implanted cells." (PMID 22936999, 2012). "For example, SEMA3B, SEMA3F, and SEMA4D have been shown to regulate tumour angiogenesis, growth and metastasisin different manners." (PMID 22926477, 2012). "Using GIT and growth analysis under cultural conditions we have shown that FUS1, SEMA3B, G21/NPRL2, RASSF1A, RASSF1C, RBSP3 (genes from AP20 and LUCA regions) and other TSGs inhibit tumour cell growth both in vitro and in vivo." (PMID 18725949, 2008).
tumor (continued). "Until now TSGs which were isolated from AP20 and LUCA regions (e.g.G21/NPRL2, RASSF1A, RASSF1C, SEMA3B, SEMA3F, RBSP3) were shown to inhibit tumour cell growth both in vitro and in vivo." (PMID 18725949, 2008). "In the metastasis group, the top shared upregulated genes were cancer-related with diverse functions, including tumor suppressors (SAMD9 and SEMA3B) and genes involved in growth, survival, cytoskeletal dynamics, motility, invasion, and metastasis (RHOBTB3, CYP24A1 and PTGS2)." (PMID 40605119, 2025). "Notably, the 3p chromosome change impacts over 500 genes, featuring tumor suppressors like BAP1, FHIT, VHL, PTPγ, SEMA3B, SEMA3F, TUSC2, and MLH1." (PMID 39201328, 2024). "Interestingly, three of the ligands with reduced expression in high PC3a and low PC4a samples, SEMA3B, SEMA3F, and SEMA3G, had both anti-angiogenic and tumor suppressor functions." (PMID 23667446, 2013). "Surprisingly, we did not observe inhibition of tumor development following the expression of sema3G, which like sema3F binds to np2, or following expression of sema3B which binds to both of the neuropilins." (PMID 22936999, 2012).
cancer (29 papers, 2004 to 2025). A tumor composed of atypical neoplastic, often pleomorphic cells that invade other tissues. "Other studies conducted in GBM U87MG and U251 cells demonstrated that the blockade of Sema3B-targeted miRNA miR-221 led to an upregulation of Sema3B protein levels, which was associated with decreased cancer cell proliferation." (PMID 31052281, 2019). "SEMA3B also promotes cancer cell apoptosis by increasing cytochrome c release and caspase-3 cleavage and inactivates proapoptotic proteins such as glycogen synthase kinase-3β, forkhead in rhabdomyosarcoma (FKHR) and mouse double minute 2 homolog (MDM-2)." (PMID 37685898, 2023). "Plexin-A2 was previously reported to convey anti-angiogenic signals induced by sema3B and to be downregulated in tumors from several types of cancer." (PMID 36658114, 2023). "It was found that class 3 semaphorins (Sema3A, Sema3B, and Sema3F) decreased with the transition from in situ to invasive cancer and Sema3A expression was only significantly reduced once invasion had occurred." (PMID 31929841, 2019). "Loss of GATA3 occurs frequently in BC and is associated with the aggressive growth and spread of the disease, and studies have demonstrated that overexpressing SEMA3B in GATA3-deficient BC cells replaces some aspects of GATA3 function, resulting in increased cancer cell survival." (PMID 37685898, 2023). "Very interestingly, we found that SEMA3B, SEMA3D, SEMA3E, and SEMA3G genes were negatively associated with RNAss and DNAss (P < .0001), where the strongest association was observed for SEMA3G with RNAss (r = − 0.49) across cancer types." (PMID 32241267, 2020). "Similarly, Sema3B was shown to induce apoptosis in cancer cells, in particularly by blocking VEGF-binding to the NRPs." (PMID 24212788, 2011). "Specifically, upregulation of SEMA3B and SEMA3F following progesterone (P4) and 1,25-dihydroxyvitamin D3 treatment increases caspase-3 activity, thereby inhibiting the growth of cancer cells." (PMID 38254014, 2024). "Sema3E, Sema4D, and Sema7A were shown to contribute to EMT, whereas Sema3B, Sema3F, and Sema5A inhibited EMT in cancer cells." (PMID 35775491, 2022). "CisPt was found to inhibit EC cell proliferation by increasing the expression of semaphorin 3B (SEMA3B), which has suppressive effects on cancer cell proliferation and angiogenesis." (PMID 36232870, 2022). "SEMA3A, SEMA3D, and SEMA3E showed relatively lower level of expression averaged across all cancer types compared to the rest of the SEMA3 family members.i.e., SEMA3B, SEMA3C, SEMA3F and SEMA3G, where SEMA3F had the highest expression." (PMID 32241267, 2020). "We found that SEMA3B, SEMA3D, SEMA3E, and SEMA3G were all negatively associated with cancer-stem like features, but SEMA3A, SEMA3C, and SEMA3F were positively correlated with DNAss, which indicates that SEMA3s may associate with cancer cell sensitivity or resistance to chemotherapy treatment." (PMID 32241267, 2020). "The methylation frequency of promoter regions of some important tumor suppressor genes, such as p16CDH1REPRIMODAPK-1 and SEMA3B, is high in GBC, and has also been well documented in other cancers." (PMID 22794276, 2012). "Some semaphorins such as Sema3B and Sema3F are considered as TSG and are very often downregulated in cancer cells." (PMID 24212788, 2011).
colon (1 paper, 2015). "SEMA3B down-regulation has been shown in lung, liver, breast, ovarian, renal and colon primary tumors using different semi-quantitative methods." (PMID 25961819, 2015).
lung (1 paper, 2015). "Moreover, our qPCR expression studies have established a strong reverse correlation between the SEMA3B mRNA level and the presence of metastases in lung ADC." (PMID 25961819, 2015).
SEMA3B also shares sentences with these, for which no sentence is quoted: esophageal squamous cell carcinoma (3 papers); diabetes (2); hepatocellular carcinoma (2); astrocytoma (1); breast tumors (1); colitis (1); coronary heart disease (1); cystic fibrosis (1); diarrheal disease (1); gastric cardia adenocarcinoma (1); ischemic stroke (1); kidney disease (1); liver cancer (1); lymphoma (1); metastatic tumors (1); nephrotic syndrome (1); non-small cell lung carcinoma (1); oral carcinomas (1); ovarian adenocarcinoma (1); ovarian tumors (1); pulmonary disease (1); respiratory infection (1); retinopathy (1); systolic heart failure (1); thyroid carcinoma (1); uveal melanoma (1); Vestibular schwannoma (1).